RAC1 (Rac family small GTPase 1)
Diseases named in the same sentence as RAC1 in open-access papers (continued):
Sharing a sentence is not in itself a finding about the gene and the disease.
tumor (continued). "In addition, some reported reactive oxygen species (ROS) involve in tumor cell migration and invasion, and a key component of NAPDH-oxidase complex is formed by RAC1, one of the major enzymatic sources of ROS in various tissues." (PMID 36452505, 2022). "It’s delighted to find that inhibition of Rac1 did not exert a protective effect on tumor cells against radiation, but also strengthened the tumor suppression effect." (PMID 35031595, 2022). "We have now proved that Rac1 inhibition could effectively reduce RILI, however, discussing the prevention and treatment of RILI must consider the impact on tumor radiotherapy." (PMID 35031595, 2022). "The role of Rac1 activation in tumor metastasis has been amply discussed, notably in the frame of various solid tumor types." (PMID 35740379, 2022). "While genetic silencing or chemical inhibition have been successfully employed so far in tumour models, no pharmacological Rac1‐specific inhibitors are currently available for clinical use." (PMID 36377725, 2022). "Furthermore, the expression levels of RAC1, CDK2, RUVBL2, and MET were upregulated in the tumor group compared to the control group and showed a noticeably positive correlation with the expression level of RHOA." (PMID 35406376, 2022). "On the other hand, our results also showed that inhibiting Rac1 has little effect on the apoptosis of LLC after radiation, without this protective effect seen in normal lung epithelial cells, Rac1 inhibition ultimately exert an anti-tumor effect." (PMID 35031595, 2022). "Cells pretreated with CTX and incubated in MCF-7-CM compared to MCF-7-CM control, showed higher inhibition of Arp2/3 (63%); the expression of Rac1, not previously affected by the tumor conditioned medium, was also reduced by CTX (43%)." (PMID 34421610, 2021). "Additionally, co-inhibition of RAC1 and BRD4 by JQ1+NSC treatment reduced MDA-MB-231-based tumor growth in vivo." (PMID 34803511, 2021). "Western blot analysis of tumor lysates shows that Rac1, Cdc42, or RhoA protein levels were not substantially decreased as a consequence of R-ketorolac treatment in vivo or after 5 days of treatment in cell culture." (PMID 33413202, 2021). "RAC1 significantly affect cell motility, invasion, and metastasis and is of a close relation with the promotion of the epithelial-mesenchymal transition (EMT) of tumor cells." (PMID 34765009, 2021). "Further analysis of the correlation of the expression level of the prognostic genes with age, gender, tumor stage and tumor grade of HCC patients showed that the expression of FYN, PPP1CC, RAC1, and SPP1 was significantly correlated with the tumor grade (P < 0.05)." (PMID 33850056, 2021). "Inhibition of Rac1 can block the proliferation and metastasis of NSCLC tumor stem cells." (PMID 34079763, 2021). "In addition, DTL activated JNK through RAC1 and upregulated FOXO1 to induce epithelial–mesenchymal transition, and the migration and invasion of tumor cells." (PMID 34635635, 2021). "Nevertheless, our data indicate that, rather than macropinocytosis as shown in keratinocyte tumor cell lines, Rac1 activation promotes E-cadherin internalization via fluid uptake that is likely to be micropinocytosis." (PMID 33914026, 2021). "Side population cells isolated from this tumor type (harboring putative CSCs) contained elevated levels of RAC1-GTP, which drove the dynamic conversion of non-CS/progenitor cells to CS/progenitor cells." (PMID 34771704, 2021). "Using this signature, together with TIAM1 and RAC1 expression, we performed hierarchical cluster analysis on RNA-sequencing (RNA-seq) data from 81 primary SCLC tumors, 44 circulating-tumor-cell-derived explant (CDX) models, and 49 SCLC cell lines." (PMID 34758330, 2021). "Further investigation demonstrated that RAC1 expression was positively regulated by C1GALT1 in LUAD, whereas silencing Rac1 could reverse C1GALT1-induced tumor growth and metastasis." (PMID 34307388, 2021).
tumor (continued). "A recent meta-analysis of 14 studies including 1793 patients demonstrates that positive Rac1 expression correlated with tumor stage, blood vessel invasion, and lymph metastasis, but not with histological differentiation." (PMID 32178475, 2020). "We further found that Porf-2 can inactive Rac1 and decrease MMP-2/9 protein level in tumor cells." (PMID 32676454, 2020). "Besides the ability to activating Rac1, Dock4 is also known to have Rap1 GEF activity in tumor cells." (PMID 32009906, 2019). "PIK3R3 was down-regulated in SKOV3 cells transfected with si-PIK3R3 accompanied with the down-regulation of Twist and Rac1, which suggests Twist and Rac1 may mediate changes in PIK3R3 expression and affecting EMT in tumor cells." (PMID 30823895, 2019). "Interestingly, RAC1 and CDC42 have actin-independent activities because they can also activate the MAP kinase pathway to affect tumor cell proliferation." (PMID 31248017, 2019). "Such a regulatory role of uPARAP in small RhoGTPase activation was in agreement with previous studies, which reported that uPARAP regulates tumor cell mobility (MCF7 and MDA-MB231) induced by urokinase (uPA) and growth factors via the regulation of Cdc42 and Rac1 activation." (PMID 30518756, 2018). "Our previous research found that by inhibiting the activity of Rac1, TIPE2 could suppress the tumorigenesis and development of tumor cells in HCC and NSCLC." (PMID 30534358, 2018). "Although without statistical significance, CRKI/II and RAC1 showed decreased expression tendencies in tumor tissues from Hca-P-ANXA5-shRNA1 than Hca-P-ANXA5-Control group on 10th d (P = 0.309)." (PMID 29802377, 2018). "We then co-transfected tumor cells with both RCC2-YFP and a constitutively activated Rac1-Q61L." (PMID 29321004, 2018). "Moreover, consistent with the Tiam1 expression, Rac1 and c-Myc expression was much higher in the 3D-cultured EL4 cells (2.1-fold and 2.3-fold, respectively) and fresh EL4 tumor (2.2-fold and 2.4-fold, respectively) than the 2D-cultured EL4 cells." (PMID 29416753, 2018). "Interestingly, the mechanical rigidity/matrix stiffness of the (tumor) microenvironment plays a crucial role in the promotion of EMT by controlling the subcellular localization and downstream signaling of RAC1 and RAC1b." (PMID 28499439, 2017). "Therefore, we tested the possibility that the WxxxE motif of mycoplasma origin suppresses tumor growth through downregulation of STAT and ERK/GSK-3β signaling by inhibiting Rac1." (PMID 28549350, 2017). "Immunofluorescence staining confirmed that TGFβ-deficient DMBA-induced skin SCC does not express RAC1 and RAC2 in contrast to anorectal SCC, where these proteins are found at the invasive front of the tumor." (PMID 28219480, 2017). "Moreover, as was the case in vitro, RAC1, p22phox, EGR1, and PTEN expression were higher in tumor tissues from EGF-treated mice compared to tumor tissues from PBS-treated control mice." (PMID 27935858, 2017). "In summary, this study shows for the first time a correlation between patient survival as well as tumor progression and IMP2/p62 expression in GBC, which might involve RAC1-induced ROS production." (PMID 29163784, 2017). "The experiments show that GLS2, but not GLS1, can directly bind to a protein called Rac1 that normally promotes the spread of tumor cells around the body." (PMID 26751560, 2016). "This allows to regulate Rac1 activity in different manners depending on the cellular process that is controlled by HA/CD44 interaction and is in line with the notion about a dual role of CD44 in tumor cells." (PMID 27163367, 2016). "However, specifically in Hinv/LE-cad tumor cells, fibronectin induced smaller cell-ECM adhesions with a fast turnover, which reflected in increased Rac1 activation and faster single cell migration." (PMID 26978651, 2016).
tumor (continued). "Rac1 activity was documented to be required for hypoxia-inducible factor 1α (HIF-1α) activation and VEGF expression elevation, which promoted angiogenesis, microscopic venous invasion, and tumor invasiveness of HCC." (PMID 26933917, 2016). "In the RAC1 example, the COAD data show a fairly consistent shift between the tumor and normal samples, whereas the LUAD tumor samples show a very wide range of exon 4 inclusion—with a few in the same range as normal samples plus some with dramatically higher PSI values." (PMID 26602693, 2016). "Rac1-GTP levels significantly increased in the tumor tissues of 87 (56%) of the 156 SCC patients compared to adjacent normal tissue, suggesting hyperactivation of Rac1 in tumor tissue." (PMID 24962779, 2014). "Reports on electrotransfer of siRNA to tumors are scarce; so far electrotransfer of siRNAs has been only used for silencing of reporter green fluorescent protein in a stably transfected tumor cells B16F10 and for silencing of vascular endothelial growth factor VEGF and Rho GTPase Rac1 genes." (PMID 23593103, 2013). "On the other hand, TGF-β can rapidly activate the Rho-family GTPases, Rac1, CDC42, and RhoA, in normal and tumor cells, although the mechanism is still unknown." (PMID 22614218, 2012). "This raises the possibility that Rac1 activation upon HA/CD44/Rac1 engagement may trigger intracellular signals that induce CD44 cleavage and enhance tumour cell migration/invasion." (PMID 22363471, 2012). "Previously, it was not practical to assess Rac1 activation status in the most commonly used format for clinical tumor specimens, formalin-fixed paraffin embedded (FFPE) tissues samples." (PMID 21358804, 2011). "In tail-vein injected NSG mice, the lung colonization of Rac1 shRNA SP cells was drastically decreased compared to scr cells and the corresponding non-SP cells showed no tumor colonization activity." (PMID 21347385, 2011). "The RAC1, CDC42, FAS, and PDGFR signaling pathways all appear in the top 15 pathways with altered consistency (yet appear lower in our list according to activity) and have been shown to play a large role in GBM tumor formation." (PMID 21542931, 2011). "Inhibition of the Rac1 activity by using a small molecule Rac inhibitor, NSC23766, resulted in decreased migration and invasion of SP cells, suggesting elevated Rac1-GTP in the SP cells contributes to these tumor cell behaviors." (PMID 21347385, 2011). "In the current work we show that Rac1 is critically involved in NSCLA cell migration, invasion and lung metastasis of SP cells, therefore serving as a useful therapeutic target by inhibiting tumor initiation and metastasis of the CSC population of NSCLA." (PMID 21347385, 2011). "Further, we demonstrate that Rac1 GTPase has a significant effect on PCa cell diapedesis, while Rac3 has a negative effect on tumor cell diapedesis." (PMID 21776386, 2011). "In PDAC dysregulated expression of Rac1 was observed in the tumour cell compartment, along with high activity of Vav1, a guanine exchange factor (GEF), which exhibits a particularly strong guanine exchange activity for Rac1." (PMID 21624123, 2011). "Our results showing that ratio of Rac1b: Rac1 is higher in controls than in ccRCC samples suggest that this isoform rather does not play tumor promoting role in ccRCC." (PMID 21082031, 2010). "Deletion of Rac1 in the vascular endothelium did not affect tumor size or tumor angiogenesis when compared with controls." (PMID 20339539, 2010). "Taken together, data from Rac1 flox/flox PDGFB-iCreER animals provided a second line of evidence that tumor growth and angiogenesis in vivo does not normally depend on Rac1." (PMID 20339539, 2010).
tumor (continued). "For this, Western blotting to detect phosphorylated and total levels of the Rac1 effectors p21 activated kinase (PAK-1/2), the RhoA effector Rho kinase (ROCK), and downstream signaling molecules AKT and ERK was done on the pooled tumor extracts from 11 mice per genotype." (PMID 20860838, 2010). "Rac1 activity and Pak1 protein levels were higher in tumor tissue and metastatic lymph node tissue than in non-tumor tissue (both P < 0.0001)." (PMID 20426825, 2010). "Collective cell migration is likely to be a primary mode of tissue movement in mammalian branching morphogenesis and tumor invasion; our findings on the AVE raise the possibility that Rac1 is also a crucial regulator of these types of mammalian collective migration." (PMID 20689803, 2010). "In order to take into account possible inter-individual variations of Rac1 activity and Pak1 protein expression in UC-UUT, we performed a comparison among paired samples of tumor tissue, metastatic lymph node tissue, and non-tumor tissue from the same patient." (PMID 20426825, 2010). "Our study showed a positive correlation between Rac1 activity and Pak1 expression in tumor tissue, while no such relation was observed in metastatic lymph node tissue." (PMID 20426825, 2010). "However, when β3-integrin levels are altered, tumor growth, tumor angiogenesis and VEGF-driven angiogenesis are enhanced and dependent on Rac1." (PMID 20339539, 2010). "Here we show that, surprisingly, the inducible-deletion of Rac1 in adult endothelial cells does not affect tumor angiogenesis or VEGF-mediated angiogenesis in adult mice." (PMID 20339539, 2010). "Using multiple in vivo approaches, we demonstrated that endothelial Rac1 is not essential for tumor growth or tumor angiogenesis in adult wild-type mice, but that these processes become Rac1-dependent in the absence of β3-integrin." (PMID 20339539, 2010). "Summarising the data, a good correlation with clinically established tumour markers was observed with RhoA-like proteins but not with Rac1 and Cdc42." (PMID 12237774, 2002). "By analysing >50 tumour samples, the amount of RhoA-like proteins (i.e. RhoA, B, C), but not of Rac1, was found to significantly increase with histological grade and proliferation index." (PMID 12237774, 2002). "Finally, in vivo experiments demonstrated that RAC1 knockdown markedly reduced ARL4C-driven pulmonary metastasis without significantly impacting subcutaneous tumor growth." (PMID 41328352, 2026). "Given that Rac1 also plays a key role in the migration of immune cells such as macrophages, it is plausible that DOCK4 may influence macrophage trafficking within the tumor microenvironment." (PMID 40529490, 2025). "The study does not thoroughly investigate the relationship between RAC1 and B cell immune subsets, thereby overlooking the complexity and dual nature of these subsets—where different B cell subsets can exhibit both pro-tumor and anti-tumor functions." (PMID 39898257, 2025). "Also, other genes (PTGS2, RAC1, and ACTN1) that are involved in tumor metastasis were found to be significantly upregulated in the CAM-DOX SH-SY5Y cells as compared to CTRL, which could be implicated in their mobilization and metastasis." (PMID 40032892, 2025). "It further shows that the in silico predicted Rac1P29S epitope similarly is naturally processed and recognized by TCR-redirected T cells, which also could be confirmed when recombinantly mutant Rac1 cDNA was expressed in tumor cells (data not shown)." (PMID 36875127, 2023). "Furthermore, upon antigen encounter, amplification of 22894 TCR-transduced CD8+ T cells was significantly higher when compared to that of the CD8+ T cells modified with 5934 Rac1-derived TCR, despite comparable T cell transduction rates and comparable recognition of Rac1P29S+ tumor cells in vitro." (PMID 36875127, 2023).
tumor (continued). "Therefore, Rac1 can be suggested as a potential therapeutic target for inhibiting EMT process, and new treatment strategy to inhibit postoperative recurrence in HCC patients with vascular invasion or advanced tumor stage." (PMID 36675278, 2023). "Therefore, we speculated that Rac1 combined with CTTN might affect the invasive and migratory abilities of tumor cells by altering the cytoskeleton." (PMID 37970440, 2023). "However, once the tumor cells step into the circulation, they no longer require increased invasion and migration abilities, instead they need to “turn off” RAC1 to reduce ROS production in order to survive at foreign sites." (PMID 36802400, 2023). "While in vitro the Rac1-specific 5934 TCR-transduced T cells performed slightly better in cytotoxicity and IFNγ release, the Rac2-specific 22894 TCR-transduced T cells expanded significantly better in vivo and induced more potent regression of the Rac1P29S expressing tumor cells." (PMID 36875127, 2023). "As for LLC, Rac1 inhibition could significantly inhibit its proliferation ability before and after radiation, while affecting little on the apoptosis and ROS production of LLC after radiation, thus the overall effect presented as tumor suppression." (PMID 35031595, 2022). "We also provide evidence that RelA/p65′s tumour promoting action in NSCLC is due to, at least in part, the downregulation of CD82 that inhibits cell migration and EMT, and the stimulation of ERK and Rac1 through the engagement of integrin-mediated signalling as revealed by bioinformatics analysis." (PMID 34503110, 2021). "Deletion of cdc42 and rac1 in a haploid strain did not result in tumor formation in maize." (PMID 33924947, 2021). "NF-κB RelA/p65 promotes lung epithelial cell tumour growth in vivo by downregulating the metastasis suppressor CD82 and enhancing the epithelial-to-mesenchymal cell transition via integrin-mediated signalling involving the mitogenic ERK, Akt1 and Rac1 proteins." (PMID 34503110, 2021). "A further evaluation of RAC1b-specific exon inclusion, using the percent spliced in (PSI) approach, showed that there is a significant and positive correlation between ESRP1 and PSI values for RAC1 in 452 tumor samples, but not in the corresponding 41 normal samples." (PMID 34439247, 2021). "RAC1 belongs to the Rho GTPase family, and many studies have revealed that Rho GTPase pathways play a critical role in regulating tumor cell cytoskeleton reorganization and cell morphology and migration; a close relation of RAC1 with EMT of tumor cells is suggested." (PMID 34765009, 2021). "High levels of RAC1 mRNA are found in primary tumour when compared with the normal tissue." (PMID 33298895, 2020). "Although the exact mechanism of the RAC1-mediated development of resistance is not clear, the role of RAC1 will be interesting to study considering the relationship of tumor cell metabolism and the production of ROS following radiation, DNA-damaging agents, and various chemotherapeutic agents." (PMID 32545340, 2020). "Some of these genes may be involved in the proliferation and invasion of tumor cells; for example, NYAP2 is reported to activate PI3K, Akt and Rac1, and mediates remodeling of the actin cytoskeleton, whereas ZNF277 regulates cell migration and invasion through phosphatase and tensin homolog (PTEN)." (PMID 32986753, 2020). "Our results demonstrate that RAC1 controls ORAI1 localization at the leading edge where this channel regulates lamellipodia formation, lamellipodial persistence, and cell directness, which are required for efficient cell migration and tumor cell invasiveness in vivo." (PMID 32313105, 2020). "High RAC1B, or a high ratio of RAC1B to RAC1 expression, may thus pose a barrier against malignant transformation and together with its potent antimigratory function in vitro, RAC1B qualifies as a genuine tumor suppressor protein." (PMID 31817229, 2019).